IQSEC3 (IQ motif and Sec7 domain ArfGEF 3)
Description:
Acts as a guanine nucleotide exchange factor (GEF) for ARF1.
Synonyms: KIAA1110; MGC30156
Tractability: PROTAC: its protein half-life has been measured.
Gene: Protein-coding gene on chromosome 12 (66,767 to 178,455, forward strand). Ensembl gene ENSG00000120645.
Subcellular location: Cytoplasm; Postsynaptic density
Subcellular location (Human Protein Atlas): Cytosol; Nucleoplasm
Pathways (Reactome):
Gene expression (Transcription): NPAS4 regulates expression of target genes
Gene Ontology:
Molecular function: guanyl-nucleotide exchange factor activity
Biological process: regulation of postsynaptic neurotransmitter receptor internalization; regulation of ARF protein signal transduction
Cellular component: cytosol; postsynaptic density; postsynaptic density membrane; cytoplasm; GABA-ergic synapse; glycinergic synapse; inhibitory synapse; postsynaptic membrane; postsynaptic specialization of symmetric synapse
Genetic constraint (gnomAD): Loss-of-function variants: 48 observed, 83.37 expected, observed/expected ratio (o/e) 0.58, 90% interval 0.46 to 0.73. The upper end of that interval is the gene's LOEUF score, 0.73, which puts it in group 2 of 6, group 1 being the genes least tolerant of losing a copy. Missense variants: 1,391 observed, 1,386.5 expected, observed/expected ratio (o/e) 1, 90% interval 0.96 to 1.05. Synonymous variants: 698 observed, 617.14 expected, observed/expected ratio (o/e) 1.13, 90% interval 1.06 to 1.2.
Homologues: Orthologues: chimpanzee IQSEC3 (99% identical), macaque IQSEC3 (96% identical), dog IQSEC3 (89% identical), rabbit IQSEC3 (88% identical), mouse Iqsec3 (86% identical), rat Iqsec3 (86% identical), guinea pig IQSEC3 (85% identical), pig IQSEC3 (66% identical), tropical clawed frog iqsec3 (61% identical), zebrafish iqsec3b (46% identical), Drosophila melanogaster siz (28% identical), Drosophila melanogaster Sec71 (13% identical), and 4 more. Paralogues in human: IQSEC2 (37% identical), IQSEC1 (36% identical), GBF1 (15% identical), ARFGEF1 (15% identical), ARFGEF2 (15% identical), MON2 (14% identical), PSD (13% identical), PSD4 (12% identical), PSD3 (12% identical), PSD2 (11% identical), CYTH3 (10% identical), CYTH1 (10% identical), and 3 more.
Diseases named in the same sentence as IQSEC3 in open-access papers:
IQSEC3 is named in the same sentence as 7 diseases in open-access papers, as found by Europe PMC text mining. Sharing a sentence is not in itself a finding about the gene and the disease. The quoted sentences say what the papers report.
breast carcinoma (2 papers, 2020 to 2024). "Alternatively, despite the lack of evidence of any apparent correlation with cancerous EMT, IQSEC3 was identified as a novel prognostic marker for breast cancer patients, and it is known that SCN1A is a possible factor in the development of chemoresistance in esophageal adenocarcinoma." (PMID 38790973, 2024). "IQSEC3 and MRGPRX1 are tumor-related genes and were first discovered in this study as a new prognostic marker for breast cancer." (PMID 33170908, 2020).
schizophrenia (1 paper, 2025). A major psychotic disorder characterized by abnormalities in the perception or expression of reality. "We observed that cg02678159 (unannotated) on chromosome 3 co‐localized (p = 0.034) with 19 SNPs (lead SNP = rs17194490) and cg19711602 (annotated to IQSEC3) on chromosome 12 co‐localized (p = 0.04) with rs4766428, which are GWAS regions previously associated with schizophrenia." (PMID 39936280, 2025).
IQSEC3 also shares sentences with these, for which no sentence is quoted: cancer (2 papers); apraxia (1); autism (1); esophageal adenocarcinoma (1); tumor (1).